H19 (H19 imprinted maternally expressed transcript)
Diseases named in the same sentence as H19 in open-access papers (continued):
Sharing a sentence is not in itself a finding about the gene and the disease.
cancer (continued). "H19 is highly expressed in many human cancers; however, its function in HCC appears to be more complex compared to other cancers." (PMID 32872482, 2020). "H19 is one of the lncRNA regulators for CSCs and its expression is up-regulated in CSC-like cells from several types of cancers." (PMID 32272875, 2020). "Thus, the crosstalk of H19 and glutathione metabolism may regulate cancer-drug resistance." (PMID 32331347, 2020). "Just like H19, CCAL is highly enriched in CAF-derived exosomes, and exosomal CCAL has been observed to be transferred from CAFs to cancer cells, promoting drug resistance." (PMID 33050576, 2020). "For LSCC prognostic lncRNAs, H19, MALAT1, NEAT1, CYTOR and SNHG12 were ranked as the first five of this directly-related-to-cancer list." (PMID 32024523, 2020). "When normal tissue stem cells undergo malignant transformation to form cancer stem cells, they acquire more differentiation plasticity, such as in fetal life when the IGF-II/H19 locus is a key regulator." (PMID 31590432, 2019). "Similarly to the scenario observed in cancer, loss of imprinting of the IGF2‐H19 locus during aging may be leading to an abnormal expression of H19, and other genes in this locus, leading to a dysfunctional mobilization of gut stem cells (Grammatikakis, Panda, Abdelmohsen, & Gorospe, 2014)." (PMID 30456884, 2019). "The signature comprised four well-known cancer-related lncRNAs, RUNX1-IT1, MALAT1, H19, and HOTAIRM1, and two less well-described transcripts LOC100190986 and AL132709.8." (PMID 32039022, 2019). "The IGF-II locus also plays a very important role in the development of numerous cancers and, in many ways, this mirrors the critical role that IGF-II/H19 plays in early embryonic development." (PMID 31590432, 2019). "Besides, since up‐regulated H19 expression rendered cardiac cancer patients with enlarged risk of unfavorable overall survival, it was insinuated that H19 could interfere with the recovery of cardiac cancer patients by depressing apoptosis and expediting growth of cancer cells." (PMID 30843379, 2019). "Top five up-regulated genes in malignant tumours were COL11A1, SFRP2, LCN2, COL2A1 and H19, while top up-regulated genes in benign tumours were MMP3, MMP1, AREG, PTHLH and SFRP2." (PMID 30517191, 2018). "Increasing lncRNAs have been reported to regulate cancer pathways and participate in cancer development, such as the well-characterized MALAT1, H19, HOTAIR and MEG3." (PMID 29849506, 2018). "Several researches have showed that the increased expression of 6 lncRNAs (H19, UCA1, TUG1, MALAT1, SPRY4-IT1, and HOTAIR) was correlated to poor prognostic outcome of cancers, those findings in consist with our results." (PMID 29870555, 2018). "For example, the lncRNAs TUG1, UCA1, SPRY4-IT1, HULC, HOTTIP, H19 and HOTAIR were found to be novel promising biomarkers for poor prognosis in human cancers." (PMID 29308050, 2018). "As expected, our microarray profiles identified several lncRNAs, which were aberrantly expressed in human cancer, such as LOC100190940, LOC100506178, H19, PVT1, VPS9D1-AS1, Linc00520, Linc00675, GNG12-AS1 CDKN2B-AS1, and CCAT1." (PMID 29523145, 2018). "TGF-β induces Slug, H19, and miR-675 through the PI3K/AKT pathway, while H19 induces Slug and suppresses E-cadherin in cancer cells." (PMID 28840253, 2018). "First, we validated 3 well-known lncRNAs (H19, HULC, and PVT1), which have been reported to be involved in a variety of cancers." (PMID 30305026, 2018). "In this study, we clarified the mechanisms by which H19 regulates PDAC metastasis, with a focus on cancer stem cells (CSCs), by using H19-overexpressing and knockdown PDAC cells." (PMID 30410672, 2018). "H19, LINC00617 (alias TUNA/TUNAR), NKX2–1-AS1, and SSTR5-AS1 were the only four that fit these thresholds and each with previous reports in cancer." (PMID 29757368, 2018).
cancer (continued). "The roles of a small number of lncRNAs such as HOTAIR, H19, and MALAT1 have been depicted in cancers, but little is known about LINC00470." (PMID 29866190, 2018). "It has already been revealed that some lncRNAs, such as HOTAIR, H19 and MALAT1, are potential biomarkers in cancer diagnosis and prognosis." (PMID 29549263, 2018). "However, we did not observe any significant association between H19 rs2107425 and cancer risk." (PMID 28159929, 2017). "Thus, H19 may play an indispensable role in the pathogenesis of cancers." (PMID 27926484, 2017). "The differentially methylated region (DMR) in the imprinted H19 locus contains two CTCF target sites that, in many cancer cells, are both hypermethylated and incapable of binding CTCF." (PMID 28587163, 2017). "Knockdown of H19 was found to downregulate SOX2, Oct4 and Nanog, as well as other cancer stem cell markers in glioblastoma and embryonic carcinoma cell lines." (PMID 28430163, 2017). "Consistently, other lncRNAs such as HOTAIR, H19 and UCA1 were also found to predict the shorter OS in cancer patients." (PMID 28410241, 2017). "H19 is induced by signals involving the EMT process and stemness, such as TGF-β, hypoxia, and HGF, suggesting a pivotal role in enhancing stemness of cancer cells via EMT." (PMID 28872613, 2017). "Thus, H19 could be considered as a potential prognostic factor for various cancers." (PMID 27672656, 2016). "The DNA methylation levels of 14q32-, H19-, MEST- and PEG3-DMRs were determined using 13 cell lines representing 6 different cancer types." (PMID 26802029, 2016). "Therefore, H19 could be used to predict the occurrence of metastasis in cancers." (PMID 27672656, 2016). "However, in gastrointestinal tumors, our result showed that the expression of H19 in DM-negative group was 2.94-fold higher than in the DM-positive group (OR = 0.34, 95% CI = 0.15–0.78, P = 0.01); insufficient sample size was the possible reason for the different results in various cancers." (PMID 27672656, 2016). "Some well-known cancer related lncRNAs such as H19, PVT1 and XIST all regulated the ‘negative regulation of cell proliferation’ process across different cancers." (PMID 27580177, 2016). "Circulating lncRNAs as biomarker for cancer diagnosis have been the subject of extensive research for years, such as POU3F3, HOTAIR, H19, MALAT-1, and so on." (PMID 27888803, 2016). "For example, the lncRNAs LOC100128593 and PGM5-AS1 showed the most pervasive down-regulation in 13 cancer types; several well-characterized lncRNAs such as HOTAIR, H19 and PVT1, also showed dysregulation in at least nine different cancer types." (PMID 27147563, 2016). "First, we targeted the following loci given the initial observation from TCGA: five imprinted domains (PEG3, H19/IGF2, DLK1/GTL2, MEST, GNAS) and four cancer genes (APC, MLL3, MGMT, ELF3)." (PMID 26338779, 2015). "There is evidence showing that H19 can affect the expression profiles of genes involved in epithelial-to-mesenchymal transition (EMT), angiogenesis, and cancer cell metastasis." (PMID 23965803, 2013). "We have used the transcriptional regulatory sequences of the H19 gene to drive expression of a toxic gene, diphtheria toxin A chain (DTA), which has suitable properties for achieving efficacious cancer cell killing." (PMID 23984081, 2013).
cancer (continued). "H19-DTA-P4-DTA, however, exhibited far enhanced efficiency in lysing the cancer cell lines, relative to each of the single promoter constructs, in T24P cells and in HT-1376 cells." (PMID 21162716, 2010). "Based on early studies of our group and others, the transcriptional regulatory sequences of the H19 and IGF2 genes emerged as candidates for cancer targeted therapy." (PMID 21162716, 2010). "In-depth analysis of epithelial cells identified H19 + myoepithelial cells (H19 + myoEpC) as the dominant malignant subpopulation, enriched in ACCB compared to other cancers and characterized by high expression of oncogenic pathways and ligands such as LAMB1 and WNT6." (PMID 41761191, 2026). "The most investigated genes were those implicated in neuroendocrine stress responses; dopamine, norepinephrine, and serotonin signalling; apoptosis; insulin secretion; neuroplasticity; reproduction; foetal growth; and cancer (e.g. MAOA, BRSK2, ADCYAP1, BDNF, DRD2, IGF2, H19)." (PMID 41070359, 2025). "The higher expression of H19 will then inhibit telomerase activity in cancer cells (without affecting hTERT expression), thereby allowing ALT to continue telomere maintenance." (PMID 40908429, 2025). "While H19/miR-675 expression was not directly examined in ATL cancer stem cells, it will be interesting to see if this locus plays a role in maintaining cancer stem cells in a Notch-independent manner." (PMID 38791169, 2024). "Similar to IGF2 and H19, DLK1 and MEG3 also perform diverse biological functions in cancers." (PMID 38812777, 2024). "Therefore, H19 offers an attractive target for therapeutic intervention in AML and related cancer types." (PMID 39199690, 2024). "The interaction between H19 and RNA-binding proteins (RBP) regulates apoptosis in cancer." (PMID 38355574, 2024). "Upon silencing of the H19 lncRNA in doxorubicin-resistant MCF-7 cells, there was a marked improvement in the sensitivity of cancer cells to chemotherapy agents such as paclitaxel and anthracyclines, accompanied by a significant decrease in the expression levels of MRP4 and MDR1." (PMID 38166752, 2024). "Determining the potential regulatory mechanisms of H19 affecting PCD could bring about wider prospects for understanding the role of H19 in cancer development and is of great importance for cancer diagnosis and treatment." (PMID 38355574, 2024). "Therefore, inhibition of H19 expression using RNAi technology and the CRISPR‒Cas9 system is a promising strategy for cancer treatment." (PMID 38355574, 2024). "Furthermore, knockdown of H19 in melatonin‐treated cells could further enhance the expression of pro‐apoptotic genes Bax and Bak, suggesting that modulation of H19 expression may contribute to the enhancement of the inhibitory effect of melatonin on cancer progress." (PMID 37307404, 2023). "Relevant studies reported that the overexpression of long non-coding RNA H19 could further activate the Ras-MAPK signaling pathway by upregulating the Ras activity and promoting the migration and invasion of CRC cancer cells." (PMID 36829196, 2023). "After careful review of the full texts, 88 articles were further excluded due to the following reasons: 30 articles were involved with other genes or other SNPs of H19, 45 studies were not relevant to cancer and 13 studies had no available data." (PMID 37480014, 2023). "Further research into several solid tumors revealed that H19 indeed interacted with a variety of transcriptional regulators and promoted the expression of genes related to EMT, thus highlighting H19 as a viable therapeutic target for cancer." (PMID 36902032, 2023). "Furthermore, the expression of QPCTL was positively correlated with SAA1, POSTN, PLA2G2A, SAA2,C6orf15, H19, PI3, etc., whose expression also affects cancer progress." (PMID 37063864, 2023). "H19 can upregulate HMGA2 by sponging the let-7 microRNA, and lincRNA-p21 can induce EMT in response to TGF-β, augmenting the invasive and metastatic potential of cancer cells." (PMID 37760852, 2023).
cancer (continued). "Together, the H19/miR-107/CDK6 axis could be exploited as a new target for both diagnosis and treatment of HCC and other cancers." (PMID 37744274, 2023). "In addition, lncRNA ROR, lncRNA H19, lncRNA PVT-1, and circ_CPA4, circ_HMCU act as miRNA sponges, and negatively regulate Let-7 expression in cancers." (PMID 37568568, 2023). "Angiogenesis stimulation via downregulation of PTEN after cancer-derived exosomal delivery of H19 and MALAT1 has not yet been reported." (PMID 36905871, 2023). "In addition, metformin action on other types of cancers by regulating ten lncRNAs including AC006160.1, Loc100506691, lncRNA-AF085935, SNHG7, HULC, UCA1, H19, MALAT1, AFAP1-AS1, AC026904.1 is described." (PMID 36849958, 2023). "First, heterogeneities were observed in most of the H19 SNPs, and subgroup analyses by source of control, cancer type, and ethnic diversity failed to completely eliminate these heterogeneities." (PMID 37480014, 2023). "Moreover, the function of lncRNA H19/miR-204-5p/NF-κB/FLIP axis was investigated in vitro, and the antigastric cancer effect of TP plus TNF-α was proved in the mice xenograft model." (PMID 36110523, 2022). "A previous study confirmed the enrichment of oncogene miR-21 in the exosomes from CRC-associated fibroblasts (CAFs) in chemoresistance to oxaliplatin, and long noncoding RNA (lncRNA) H19 is highly expressed in the CAFs of CRC patients and with a marked increase with cancer progression." (PMID 36230645, 2022). "The very indication that this H19 affects MET comes through the miRNA it targets as this miRNA is very well known to be involved in regulation of EMT, thus making this miRNA an attractive cancer biomarker." (PMID 35402278, 2022). "Interestingly, some of these lncRNAs (such as ANRIL, H19, and HOTAIR) are also dysregulated in cancer, creating a link between the ncRNA expression profile and cancer risk in obese people, as reported by Yau and colleagues." (PMID 36012617, 2022). "Similar to H19, IGF2 is also highly active in various human cancers." (PMID 36246634, 2022). "Researchers investigated the RNA expression data of CRC patients obtained from 622 CRC cancer tissues and 51 adjacent nontumor normal tissues from the TCGA data portal, and the results showed that H19 is highly expressed in human CRC tissues." (PMID 34977037, 2021). "Both techniques have shown promise in cancer research, miR-CATCH has been applied to MSLN mRNA, which is overexpressed in Malignant Pleural Mesothelioma and miR-CLIP was validated in Hela cells revealing the lncRNA H19 as a target of miR-106a." (PMID 33803328, 2021). "Lnc-H19 and MALAT1 has been proved to be promising targets for cancer therapy." (PMID 34041287, 2021). "Additionally, upregulated genes included H19, IGF2 and DLK1, all regulated by PLAGL1 and with known functions in tumorigenesis of different cancers." (PMID 34355256, 2021). "IGF-II/H19 was the first gene to be identified as being “imprinted”—where the paternal copy is not transcribed—a silencing phenomenon lost in many cancer types." (PMID 33669311, 2021). "Also, Linc00319, H19, AFAP1-AS1, SNHG7, HOTTIP, linc01023, DLEU1, and NEAT1 have been identified as prognostic markers in diverse kinds of cancer." (PMID 33768092, 2021). "Accumulating lines of evidence have proven that lncRNAs could be targets for cancer diagnosis and may be suitable biomarkers, such as HOTAIR, H19, and XIST." (PMID 32785606, 2020). "Contrarily, miR-148a-3p targeting the long non-coding RNA H19 (lncRNA H19) and the DNA methyltransferase enzyme DNMT1 shows to suppress migration and invasion of cancer cells and may have prognostic value in the future." (PMID 33521000, 2020). "The most prolific lncRNAs, with ≥16 recorded cancer types, are HOTAIR, MALAT1, MEG3 and H19." (PMID 32024996, 2020). "We summarize how H19 may regulate CSC division and cancer cell reprogramming, thus affecting metastasis and drug resistance." (PMID 33291403, 2020).
cancer (continued). "H19 promotes EMT and cancer metastasis through a variety of mechanisms." (PMID 33267897, 2020). "Moreover, H19 induces PKM2 expression, which is involved in the Warburg effect during cancer progression." (PMID 32331347, 2020). "Moreover, inhibition of H19 expression by siRNA resulted in significantly decreased proliferation, invasion, as well as increased apoptosis of ATC cancer cells (8505C)." (PMID 33126409, 2020). "In this review, we will first describe H19 and its action in cancer development in a general way, and then overview how H19 may regulate CSC division and cancer cell reprogramming." (PMID 33291403, 2020). "NSUN2 may affect these signaling pathways by regulating the binding of H19 RNA to G3BP1 and then affect the progression and malignancy of cancer cells." (PMID 32978516, 2020). "In a preclinical setting, lncRNAs have been suggested as potential diagnostic or prognostic biomarkers affecting a variety of tissues including the heart (MALAT1), reproductive system (H19), muscle (linc‐MD1), and several cancer types (MALAT1, H19, MEG3, HOTAIR) (reviewed in 81, 82)." (PMID 32100288, 2020). "H19 is a 2.3-kb-long, spliced and polyadenylated lncRNA that is, similarly to IGF2BP1, expressed during embryonic development and reactivated in several types of cancer." (PMID 32340118, 2020). "Another lncRNA H19, which is overexpressed in patients of CRC, can regulate the expression levels of β‐catenin by competing with miR‐200a, thus resulting in more activated proliferation and metastasis of cancer cells." (PMID 32860492, 2020). "Additionally, several lncRNAs (e.g., H19, CCAT1 and CCR492) have been reported to be ceRNA by sponging let-7 miRNA family in different types of cancer." (PMID 31514732, 2019). "Other ceRNAs like H19 in the network, such as pseudogene RPLP0P2, may also play a pivotal role in cancer progression by regulating the expression level of mRNAs through sponging various miRNA." (PMID 31164794, 2019). "Taken together the evidence suggests that H19 up-regulates various cancer-related mRNA expression levels via serving as a ceRNA, and participates in the PI3K–Akt signaling pathway in this manner, playing a key role in promoting cancer progression." (PMID 31164794, 2019). "Dysregulation of H19, HOTAIR, and MALAT1 was observed in many types of cancer." (PMID 31827510, 2019). "In this cohort, we further explored the gene-environmental factor interaction of H19 promoter SNPs rs493010, rs11042170, and rs2735970 with clinicopathological parameters of CRC patients including gender, body weight, smoking and family history of cancer." (PMID 31452627, 2019). "Results from a meta-analysis showed that high H19 expression levels were inversely correlated with OS and prognosis in many types of cancer, suggesting a potential negative prognostic role for this biomarker." (PMID 31827510, 2019). "H19 strong antagonism with expression of apoptotic genes in normal tissue is practically cancelled in cancer, confirming its important role in cancer proliferation revealed by several authors." (PMID 29416781, 2018). "Here, we showed that in PDAC cells, H19 promotes sphere formation, but not stemness-marker expression or transporter expression and anti-cancer-drug resistance." (PMID 30410672, 2018). "Likewise, a lot of previous meta-analyses investigated the relationship between the other lncRNAs expression and prognosis of corresponding cancers, such as HOTAIR, H19 and MALAT1." (PMID 29805767, 2018). "Therefore, we examined the mechanisms by which H19 regulates PDAC metastasis, with a focus on cancer stem cells (CSCs), by using PDAC cells in which H19 was either overexpressed or depleted." (PMID 30410672, 2018). "To understand the extensive role of H19 in cancers, we then implemented a meta-analysis of Kaplan-Meier survival analysis to evaluate the prognostic power of H19 in non-female cancers (25 common cancers) from TCGA." (PMID 27926484, 2017).